HIF1A (hypoxia inducible factor 1 subunit alpha)
Diseases named in the same sentence as HIF1A in open-access papers (continued):
Sharing a sentence is not in itself a finding about the gene and the disease.
glioblastoma (continued). "Therefore, we examined the effect of experimentally imposed uninterrupted or cycling hypoxic stress on HIF-1α and NF-κB activation in glioblastoma cells." (PMID 26711814, 2015). "However, both HIF-1α and NF-κB protein levels in glioblastoma cells under cycling hypoxia stress were higher than those in cells under uninterrupted hypoxia stress." (PMID 26711814, 2015). "Removal of the HIF1α to IGFBP2 connection had minimal effect on the glioblastoma growth." (PMID 25884993, 2015). "In addition, GRIM-19 has been reported to negatively regulate HIF-1α level in a Stat3-dependent manner in glioblastoma cells." (PMID 25575809, 2015). "Moreover, glioblastoma cells, U87 and U251, were treated with specific HIF-1α (YC-1) and NF-κB (Bay 11-7082) inhibitors during cycling hypoxic treatment." (PMID 26711814, 2015). "Proteomic studies of glioblastoma cells after treatment with carnosine revealed significantly reduced expression of von Hippel-Lindau binding protein 1 (VBP1), a protein that binds to the von Hippel-Lindau protein and thus is linked to HIF-1α signaling." (PMID 24886661, 2014). "CD133 expression is enhanced under hypoxic conditions via HIF-1α/mTOR signaling in glioblastoma." (PMID 25301737, 2014). "The transcriptional activity of HIF-1α is high in glioblastoma cells." (PMID 24465898, 2014). "IDH1 mutation itself may not be sufficient to account for a general HIF-1α-driven hypoxia in glioblastoma, as elevated HIF-1α levels are usually confined to severely hypoxic areas of necrosis such as palisades." (PMID 23451042, 2013). "To support this, we over-expressed HIF-1α in glioblastoma cells and measured the changes of GSCs." (PMID 23391506, 2012). "Firstly, because glioblastoma is characterized by its uncontrolled vascularization and high expression of miR-17 in tumor samples, miR-17 may take part in the process of glioblastoma angiogenesis by activating HIF-1α and VEGF indirectly." (PMID 23391506, 2012). "Since HIF-1α is involved in response to drug treatment in glioblastoma, our data suggested that miR-17 could confer drug resistance to the cells by regulating the PTEN/HIF-1α pathway." (PMID 23391506, 2012). "We further address the impact of HIF-1α inhibition on CoCl2 responding glioblastoma cell types." (PMID 22134773, 2012). "All 11 glioblastomas were positive for all 3 hypoxia-related markers (HIF-1α, GLUT-1 and CA IX)." (PMID 22825389, 2012). "Piezo1 is highly expressed and co-localized in extensively angiogenic GBM endothelial cells and promotes aberrant angiogenesis in glioblastoma through the HIF-1α/VEGF pathway." (PMID 40061015, 2025). "Pseudopalisades, a characteristic pathological feature of glioblastoma (GBM), are driven by HIF-1α upregulation in hypoxic tumor cells, which promotes their migration away from regions of vascular occlusion and necrosis." (PMID 40443737, 2025). "Western blot detection under hypoxic conditions distinctly reveals an increase in HIF-1α protein expression in glioblastoma, emphasizing the pivotal pathogenic role played by the HIF-1α protein in GBM." (PMID 39781344, 2025). "Hence, we wondered whether the HBO-induced reduction in HIF1α/HIF2α expression could be a key factor in the inhibition of stemness in glioblastoma." (PMID 40370575, 2025). "However, in a phase of cancer progression where TSGA10 is downregulated (e.g., glioblastoma), perhaps under HIF-1α pressure, disrupted coupling at Complex III may promote electron leakage, elevating ROS to mutagenic levels that drive oncogenic mutations." (PMID 40507237, 2025). "The expression of HIF1α, which correlates with rOEF, may reflect the level of hypoxia in tumor tissue and stimulate more pronounced local angiogenesis, a characteristic feature of glioblastomas." (PMID 39684754, 2024). "Clinical studies consistently report the elevated expression of HIF1α in glioblastoma (GBM) tissues, suggesting its pivotal role in tumor progression." (PMID 38893207, 2024).
glioblastoma (continued). "Glioblastoma multiforme (GBM) samples showed high expression of MCUb and hypoxia‐inducible factor 1‐α (HIF1α), a transcriptional regulator typically induced by hypoxia, both localized in areas bordering necrosis." (PMID 36538269, 2023). "An investigation of glioblastoma multiforme tumor (GBM) cells showed that AGR2 expression was regulated by HIF-1α and directed glioblastoma cell growth and the vascularity of tumors." (PMID 37175601, 2023). "Interestingly, a recent study has provided evidence that downregulating HIF-1α in glioblastoma could improve temozolomide response, suggesting that inhibiting HIF-1α could be a valuable addition to the current standard treatment for the disease." (PMID 36115843, 2022). "Therefore, celastrol may downregulate angiogenesis and VMF via the PI3K/AKT/mTOR/HIF-1α pathway in glioblastoma." (PMID 34575983, 2021). "Moreover, ganetespib and palbociclib diminished HIF1α expression in T98G glioblastoma cells." (PMID 34686682, 2021). "Thus, these manifold lines of evidence showed that prolonged hypoxia induced by CoCl2 could trigger hypoxic insults to human and mouse TMZ-resistant glioblastoma cells via a HIF-1α-dependent mechanism." (PMID 34136065, 2021). "As covered in Chaperone-Mediated Autophagy in Glioblastoma, CMA decreases HIF-1α activity in GBM cells." (PMID 33312955, 2020). "Furthermore, we found a positive correlation between CA20 and hypoxic levels in glioblastoma multiforme that is particularly interesting, due to its highly hypoxic microenvironment and HIF-1α levels, also shown to enhance migration and invasion of its tumour cells." (PMID 30856170, 2019). "A literature review identified DUSP4, HIF-1α, and COL8A2 as being linked to ERK signaling, and analysis of a published dataset of chromatin immunoprecipitation sequencing (ChIP-seq) data for Bmi1 in neural stem cells and glioblastoma cells identified Dusp4 as a direct Bmi1 target gene." (PMID 29212025, 2017). "Since normal tissue stem cells and CSCs tend to share common underlying mechanisms to control their stemness, we applied the concept of HIF-1α-regulated quiescence to GSCs in order to clarify whether a similar niche may play important roles in the pathophysiology of glioblastoma." (PMID 26799577, 2016). "Therefore, we proposed that the activation of HIF-1α and NF-κB induced by ROS under cycling hypoxia could result in Bcl-xL induction and allow the survival of glioblastoma cells." (PMID 26711814, 2015). "Therefore, we next examined whether the regulation of Bcl-xL in glioblastoma cells was affected by cycling hypoxia-induced HIF-1α and NF-κB activation." (PMID 26711814, 2015). "HIF1-α knockout mice (HIFko) with glioblastoma (GBM) tumors, show a decrease in angiogenesis when compared to HIF functional mice with tumors." (PMID 26932379, 2014). "Notably, HIF-1α is often found overexpressed in glioblastoma." (PMID 23391506, 2012). "Based on the results of the PPI network and KEGG enrichment analysis, AKT1, HIF1A, CDH1, and NFKB1 were identified as vortioxetine targets that also regulate glioblastoma." (PMID 40312983, 2025). "The relative HIF-score was previously derived from protein data by combining HIF-1α and 6 HIF-regulated proteins into a single relative score for each glioblastoma sample." (PMID 40123902, 2025). "Iron depletion therapy must be carefully managed to avoid inducing hypoxia and subsequent upregulation of hypoxia‐inducible factor 1‐alpha (HIF‐1α), which can promote chemoresistance and tumor recurrence in glioblastoma (GBM)." (PMID 40285641, 2025). "In glioblastoma, Lys acetylation of PRMT3 promotes nuclear translocation, leading to co-localization with nuclear HIF-1α and thus prioritizing HIF-1α methylation." (PMID 41583428, 2025). "KIF4A promotes malignant progression of glioblastoma and transmission of TMZ resistance in the tumor microenvironment through the HIF1A/VEGFA axis." (PMID 41084153, 2025).
glioblastoma (continued). "HIF-1α, a transcriptional regulator of ABCB1, also exhibited a different pattern in MDR glioblastoma and NSCLCs that mirrors ABCB1 expression." (PMID 40006556, 2025). "CRISPR/Cas9 targeting of HIF-1α could be a means of overcoming NK-cell-function-suppressive hypoxia circumstances in NK-cell-based immunotherapy for cancer, including glioblastoma (GBM)." (PMID 38892084, 2024). "The synergistic blockade of the HIF1α-LGMN axis, aided by AMPK inhibition and anti-PD1 antibody therapy, represents a promising approach to interrupting glioblastoma progression." (PMID 38893207, 2024). "For example, one study showed that 6-phosphofructo-2-kinase/fructose-2, 6-biphosphatase 4 (PFKFB4) binds to FBXO28 to regulate the ubiquitination and proteasomal degradation of HIF-1α, promoting HIF-1α signaling in glioblastoma." (PMID 38267923, 2024). "In glioblastoma multiforme, MSH6 can affect the tumor microenvironment by regulating HIF1A to accelerate tumor metastasis." (PMID 38879468, 2024). "Mechanistically, we revealed that FBXO22 stimulates the activation of the HIF-1α-VEGFA pathway by directly binding and mediating VHL ubiquitination degradation and promoting the malignant progression of glioblastoma." (PMID 38519492, 2024). "In patient-derived glioblastoma cell lines, ATP6AP2 and AGTR1 were upregulated after chemoradiotherapy and correlated with an increase in HIF1A expression." (PMID 38607073, 2024). "Hypoxia-induced M2 phenotype macrophages promote the stemness traits of glioblastoma through VEGF secretion, which is mediated by HIF-1α activation." (PMID 38424190, 2024). "The result showed that except for the glioblastoma multiforme and esophageal carcinoma, COPZ1 had a positive correlation with the HIF1A in most of the rest cancer." (PMID 37107648, 2023). "A specific signaling pathway between GSCs and microglia, the CLOCK-olfactomedin-like 3 (OLFML3)-HIF1α-legumain (LMGN)-cluster of differentiation 162 (CD162) axis, has been identified and serves as a potential therapeutic target for glioblastoma." (PMID 38173841, 2023). "TEMPOL is one such example and has been shown to inhibit both hypoxia-inducible factor 1α (HIF-1α) and hypoxia-inducible factor 2 α(HIF-2α) in glioblastoma." (PMID 37213306, 2023). "In glioblastoma, the aberrant NOX4-dependent ROS generation affects the regulation of FOXM1 by mediating HIF1α stabilization." (PMID 36768405, 2023). "TGF-β1 is also required for the NOX4-dependent stabilization of HIF1α and of its nuclear accumulation, which results in metabolic reprogramming and in promoting the epithelial mesenchymal transition (EMT) of glioblastoma." (PMID 36768405, 2023). "Alternatively, in glioblastoma (GBM), specific protein 1 (SP1) plays a crucial intermediary role in HIF-1α-mediated H19 expression via binding GC-boxes in the H19 promoter." (PMID 35842651, 2022). "Expression analysis of the Elvidge HIF-1α and HIF-2α signature in a cohort of glioblastoma patients (n = 152), available from The Cancer Genome Atlas (TCGA), revealed a positive correlation between PFKFB4 expression (r = 0.657) and HIF signaling." (PMID 36115843, 2022). "Together, the HIF-1α/miR-224-3p/ATG5 signaling pathway affects the motility and chemotherapy sensitivity of glioblastoma tumor cells by regulating hypoxia-induced autophagy." (PMID 36157351, 2022). "HIF-1α and HIF-2α are present in the immunohistochemical staining of glioblastoma biopsies in these peri-hypoxic niches." (PMID 35054779, 2022). "The potential mechanism of radiosensitization was achieved by decreasing the ratio of Bcl-2/Bax, inducing apoptosis in glioblastoma cells, and downregulating the expression of HIF-1α, MMP-2, and Wee1 via the HIF-1α/MMP-2 signaling pathway." (PMID 35744822, 2022). "Topotecan, a United States Food and Drug Administration-approved anti-glioblastoma drug, can reduce overall cell SUMOylation, CDK6, and HIF-1α levels and regulate the cell cycle, but the specific target is not clear." (PMID 33898460, 2021).
glioblastoma (continued). "NOX4 knockdown in our glioblastoma cells attenuated the activity of PI3K, p-AKT, and HIF-1α under treatment with TGF-β1." (PMID 34257808, 2021). "In vitro and in vivo experiments showed that in both the glioblastoma cells and glioblastoma stem cells, DCA increased apoptosis and reactive oxygen species, while decreasing mitochondrial potential and HIF-1α." (PMID 34298883, 2021). "Because intratumoral hypoxia is a common feature of solid tumors, particularly in glioblastoma, and HIF-1α is downstream of NOX4-derived ROS, we clearly elucidated that NOX4-derived MitoROS induced FOXM1 overexpression by stabilizing HIF-1α." (PMID 34740322, 2021). "As expected, Western blot analysis demonstrated that in glioblastoma cells, overexpression of NOX4 induced HIF-1α protein expression, whereas the opposite was true upon NOX4 knockdown." (PMID 34740322, 2021). "Specifically, peptide treatment significantly reduced HIF-1α and HIF-2α levels in glioblastoma cells by inducing a drastic inhibition of PI3K/Akt and ERK1/2 signaling cascades, involved in uncontrolled cell proliferation." (PMID 34439613, 2021). "In direct contrast, a more recent study showed that IL-8 secreted by glioblastoma and other microenvironmental immune cells promotes glioma migration, invasion, and mesenchymal transition via the STAT1/HIF-1α/Snail cascade." (PMID 33498872, 2021). "In glioblastoma-derived cell lines, Parkin knockout facilitates HIF-1α accumulation in normoxia while blocking hypoxic HIF-1α stabilization." (PMID 34439955, 2021). "FGFR1 induces glioblastoma radioresistance through the PLCγ and HIF-1α pathways, and inhibition of FGFR1 radiosensitizes glioblastoma cells." (PMID 34127812, 2021). "Interestingly, Bao and colleagues demonstrated that within glioblastoma cells methylation of this residue or mutation to arginine did not alter promotor occupancy of p300 nor the binding of p300 and other co-regulators to HIF1α." (PMID 33088284, 2020). "Similarly, a recent work on glioblastoma (GBM) revealed that HIF-1α fosters branched-chain amino acid (BCAA) metabolism by upregulating the expression of both BCAA transporter LAT1 and BCAA metabolic enzyme BCAT1." (PMID 32932943, 2020). "Recently, we demonstrated that CAR-T cells targeting carbonic anhydrase IX (CAIX), a protein involved in HIF-1a hypoxic signaling, is a promising CAR-T cell target in an intracranial murine glioblastoma model." (PMID 31935881, 2020). "Glioblastoma (GBM) undergoes malignant progression under hypoxic conditions, which are mainly regulated by HIF1α and HIF2α3–6." (PMID 33208727, 2020). "Carbonic anhydrase IX (CAIX), an enzyme involved in hypoxia inducible factor 1 alpha (HIF-1α) hypoxic signaling, is a promising target for chimeric antigen receptor-T (CAR-T) cells in an intracranial mouse model for glioblastoma." (PMID 32751469, 2020). "Both HIF-1a and HIF-2a are expressed in cell culture and spheroid models of glioblastoma including by U87 cells." (PMID 32566921, 2020). "In hypoxic regions of glioblastoma, both HIF-1α and ASPH were highly expressed, particularly in more aggressive mesenchymal subtype of glioblastoma, suggesting a possible involvement of ASPH in mesenchymal transition." (PMID 32811566, 2020). "To investigate the antiangiogenetic mechanism of stellettin B, we detected the protein expression of HIF-1α, p-Stat3, and the downstream angiogenesis effector, VEGF, which was inhibited by stellettin B treatment in glioblastoma cell lines." (PMID 30769863, 2019). "Furthermore, Stat3 is an activator of the epithelial-mesenchymal transition (EMT) process in glioblastoma, both through TGFβ and HIF-1α, thus enhancing tumour high motility, invasiveness and chemo resistance, which could account for the positivity of cells at the invasion front." (PMID 31690341, 2019). "Collectively, the results demonstrated that stellettin B downregulates p-Stat3 and HIF-1α inhibits VEGF expression and secretion in glioblastoma cells." (PMID 30769863, 2019).
glioblastoma (continued). "Oncogenic miR-17 promotes cell motility and invasion through PTEN suppression and subsequent HIF1α and VEGF up-regulation in glioblastoma." (PMID 31366089, 2019). "Our previous results have shown that HIF1α regulates the PDK1/ EGFR interaction in the mitochondria and transcriptionally regulates PDK1 in glioblastoma." (PMID 28410193, 2017). "We confirmed the inhibitory effect of SAHA on the expression of HIF-1α and HIF-2α in glioblastoma (U87 MG) and osteosarcoma (U2OS and MG-63)." (PMID 28915577, 2017). "The expression of Hif-1α, PTEN and H19 levels were analyzed in 22 human glioblastoma tissues (GBM) and 15 adjacent normal brain tissues (NBT) removed from patients." (PMID 28327666, 2017). "In this study we show that US28 signaling results in activation of the HIF-1α/PKM2 feedforward loop in fibroblasts and glioblastoma cells." (PMID 27602585, 2016). "To discuss the roles of HIF-2α in the stemness and quiescence of glioblastoma cells within the peri-necrotic niche, which is the focus of our study, we compared the localization of HIF-2α+ cells with that of SOX2+ HIF-1α+ RNApII-S2P-/low cells." (PMID 26799577, 2016). "In our series of 21 glioblastoma cases, foci of large ischemic necrosis were observed in 20 cases, among which the existence of SOX2+ HIF-1α+ RNApII-S2P-/low cells near large ischemic necroses was found in 16 cases." (PMID 26799577, 2016). "Similar findings were found in prostate PC-3 and glioblastoma U87 cells, suggesting a potential exclusive contribution of S1P1 receptor subtype in mediating the effect of S1P on both HIF-1α and HIF-2α content in cancer cells." (PMID 26974204, 2016). "HIF-1α or CA9 expression was decreased in five of the six tumors, whereas the decreased expression of these markers was noted in only one of the 11 control glioblastomas." (PMID 27244880, 2016). "Recruitment of endothelial and pericyte progenitor cells to promote neovascularization in glioblastoma and regulate the invasion of GBM cells could be induced by HIF1α, partly through increases in SDF1α." (PMID 26977157, 2016). "In fact, the top four rate constants that glioblastoma growth was most sensitive to when individually perturbed were the production of HIF1α (k8), production of IGFBP2 (k1), growth rate due to HIF1α (k11) and promotion of HIF1α by IGFBP2 (k10)." (PMID 25884993, 2015). "HIF-1α-, GLUT-1- and CA IX-positive staining was found in all 11 glioblastomas, showing a preferential expression in tissue areas adjacent to necroses." (PMID 22825389, 2012). "Also, since HIF1A regulates the AKT and PDGFs pathways that support glioblastoma development, therapies that directly target HIF-1α alone show meaningful antitumor effects." (PMID 41575610, 2026). "P4HA1, an enzyme involved in collagen hydroxylation and hypoxia response, has been recently shown to regulate succinylation in glioblastoma by increasing intracellular succinate and enhancing PGK1 K191/K192 succinylation, which stabilizes PGK1 and promotes aerobic glycolysis via the HIF1α/ATF3 axis." (PMID 40463370, 2025). "The observed effects on HIF-1α and MGMT gene expression suggest that LB-100 may enhance the efficacy of approved therapies like temozolomide, commonly used for glioblastoma therapy." (PMID 40006556, 2025). "In addition, due to the knockdown of HIF1a, the GSC population decreased significantly, which indicates the importance of HIF1a in the acquisition of glioblastoma cells of an undifferentiated phenotype and further maintenance of the GSC population." (PMID 39768176, 2024).